SLAMF7 (SLAM family member 7)
Description:
Self-ligand receptor of the signaling lymphocytic activation molecule (SLAM) family. SLAM receptors triggered by homo- or heterotypic cell-cell interactions are modulating the activation and differentiation of a wide variety of immune cells and thus are involved in the regulation and interconnection of both innate and adaptive immune response. Activities are controlled by presence or absence of small cytoplasmic adapter proteins, SH2D1A/SAP and/or SH2D1B/EAT-2. Isoform 1 mediates NK cell activation through a SH2D1A-independent extracellular signal-regulated ERK-mediated pathway. Positively regulates NK cell functions by a mechanism dependent on phosphorylated SH2D1B. Downstream signaling implicates PLCG1, PLCG2 and PI3K. In addition to heterotypic NK cells-target cells interactions also homotypic interactions between NK cells may contribute to activation. However, in the absence of SH2D1B, inhibits NK cell function. Also acts inhibitory in T-cells (By similarity). May play a role in lymphocyte adhesion. In LPS-activated monocytes negatively regulates production of pro-inflammatory cytokines. Isoform 3 does not mediate any NK cell activation.
Synonyms: CRACC; CD319; CS1; 19A
Tractability: Antibody: an approved drug acts on it; its Gene Ontology location is reachable by antibodies, with high confidence; UniProt predicts a signal peptide or a membrane-spanning region. PROTAC: ubiquitination databases record sites on it. Other modalities: a drug acting on it is in phase 2 or 3 trials.
Target class: Membrane receptor
Gene: Protein-coding gene on chromosome 1 (160,739,057 to 160,754,821, forward strand). Ensembl gene ENSG00000026751.
Subcellular location: Membrane
Subcellular location (Human Protein Atlas): Vesicles
Pathways (Reactome):
Immune System: Immunoregulatory interactions between a Lymphoid and a non-Lymphoid cell
Gene Ontology:
Molecular function: identical protein binding
Biological process: cell adhesion; immune response; natural killer cell activation; natural killer cell mediated cytotoxicity; T cell activation
Cellular component: external side of plasma membrane; plasma membrane; membrane
Genetic constraint (gnomAD): Loss-of-function variants: 21 observed, 30.6 expected, observed/expected ratio (o/e) 0.69, 90% interval 0.49 to 0.99. The upper end of that interval is the gene's LOEUF score, 0.99, which puts it in group 4 of 6, group 1 being the genes least tolerant of losing a copy. Missense variants: 354 observed, 382.78 expected, observed/expected ratio (o/e) 0.92, 90% interval 0.85 to 1.01. Synonymous variants: 159 observed, 150.78 expected, observed/expected ratio (o/e) 1.05, 90% interval 0.93 to 1.2.
Homologues: Orthologues: chimpanzee SLAMF7 (98% identical), macaque SLAMF7 (90% identical), rabbit SLAMF7 (62% identical), guinea pig SLAMF7 (61% identical), dog SLAMF7 (61% identical), pig SLAMF7 (58% identical), rat Slamf7 (50% identical), mouse Slamf7 (46% identical), zebrafish si:cabz01074946.1 (13% identical). Paralogues in human: CD84 (28% identical), SLAMF6 (26% identical), LY9 (26% identical), SLAMF9 (22% identical), CD244 (20% identical), CD2 (19% identical), SLAMF1 (18% identical), SLAMF8 (18% identical), CD48 (11% identical).
Diseases named in the same sentence as SLAMF7 in open-access papers:
SLAMF7 is named in the same sentence as 109 diseases in open-access papers, as found by Europe PMC text mining. Sharing a sentence is not in itself a finding about the gene and the disease. The quoted sentences say what the papers report.
myeloma (144 papers, 2013 to 2026). "Elotuzumab targets SLAMF7, causing infusion-related reactions and potentially contributing to cytopenias and infection risk, exacerbated by myeloma-related immunosuppression." (PMID 39065666, 2024). "SLAMF7 encodes surface antigen CD319, which is a stable marker of both normal and malignant plasma cells in multiple myeloma." (PMID 37190123, 2023). "SLAMF7 has been linked to several diseases, for example, it is associated with systemic lupus erythematosus, multiple myeloma and immunoregulatory interactions." (PMID 33593402, 2021). "SMM patients with an evolving pattern of the M-protein showed an increase in genes associated to myeloma (SLAMF7, CD79A, CD79B) and AXL." (PMID 34880879, 2021). "Elotuzumab is a humanized IgG1 anti-SLAMF7 mAb under clinical investigation for the treatment of relapsed/refractory newly-diagnosed MM, and high-risk smoldering myeloma." (PMID 25287778, 2015). "Collectively, these findings redefine SLAMF7 as both an immune cell activator and a dual-function antigen in myeloma pathobiology, with its membrane and soluble forms exerting opposing effects that are therapeutically targetable by elotuzumab." (PMID 41511330, 2025). "For instance, SLAMF7 has been identified as a potential therapeutic target in multiple myeloma, with its expression correlating with disease progression." (PMID 41162970, 2025). "SLAMF7 is uniformly expressed on malignant plasma cells in newly diagnosed myeloma and is still present in relapsed myeloma after intensive therapy, making it an ideal target." (PMID 41228264, 2025). "Signaling Lymphocyte Activation Molecule Family member 7 (SLAMF7) represents a potential target for CAR T-cell therapy in the treatment of multiple myeloma (MM), and it is a promising alternative to classic BCMA-CAR therapy." (PMID 41228264, 2025). "Secondly, Ad[CE1A] replication in human myeloma cells was demonstrated via E1A expression and infectious progeny production, correlating strongly with SLAMF7 expression, which evidences SLAMF7 promoter control of E1A expression." (PMID 40247106, 2025). "Beyond direct tumor promotion, sSLAMF7 activates SLAMF7+ macrophages and fosters T-cell exhaustion through SLAMF7-mediated cross-talk, contributing to the immunosuppressive microenvironment of refractory myeloma." (PMID 41511330, 2025). "The analysis showed that BCMA, ICAM3 (CD50), CD221, and CS1 (SLAMF7) are the most abundantly expressed markers at all stages of myeloma, with BCMA, ICAM3, and CD221 being expressed at significantly higher levels in diseased rather than precursor PCs." (PMID 39991572, 2025). "Confirmed SLAMF7 expression on myeloma cells would be demonstrated by flow cytometry or immunohistochemistry." (PMID 41228264, 2025). "Its therapeutic efficacy is mainly derived from NK cell activation via SLAMF7–EAT-2 signaling and ADCC against SLAMF7+ myeloma cells." (PMID 41511330, 2025). "ELO enhances SLAMF7-SLAMF7 interactions between NK cells and myeloma cells, sending costimulatory signals that enhance killing." (PMID 41228264, 2025). "Other studies in this section were designed against non-T cell malignancies, of which three utilized SLAMF7 (CSI) plus TRAC KO anti-SLAMF7 CAR T cells against multiple myeloma (MM)." (PMID 41354926, 2025). "Signaling lymphocytic activation molecule F7 (SLAMF7), a molecule expressed on a subset of T cells, activated B cells, macrophage, and myeloma cells, is an attractive target to explore based on studies showing SLAMF7 expression in a subset of AITL cases." (PMID 39877932, 2025). "This variant X encodes a secreted protein that forms homotypic interactions with membrane SLAMF7 and promotes the proliferation of SLAMF7+ myeloma cells." (PMID 41511330, 2025). "CD138+ myeloma patient-derived plasma cells also displayed significantly higher CS1/SLAMF7 expression than myeloma CD138- BMMCs, HD CD138+ plasma cells and HD CD138- BMMCs." (PMID 40247106, 2025).
myeloma (continued). "In contrast, in the same study, pomalidomide significantly decreased CS1 via targeting IKZF1, a pivotal transcriptional activator of SLAMF7 in myeloma cells." (PMID 40247106, 2025). "We thus performed a therapeutic experiment comparing romidepsin (approved use in relapsed/refractory PTCLs), rituximab, elotuzumab (anti‐SLAMF7 antibody approved for use in multiple myeloma), and combinations of these agents." (PMID 39877932, 2025). "SLAMF7 was also chosen as a target over other myeloma markers, such as B-cell maturation antigen (BCMA) and CD38, because BCMA expression can be downregulated or lost entirely in patients who have undergone BCMA-targeted therapies." (PMID 40247106, 2025). "Expanding on previous work, a novel SLAMF7-promoter driven oncolytic Ad5 (Ad[CE1A]), specifically targeting SLAMF7 expressing cells, was generated and its efficacy against myeloma (cell lines, patient-derived cells and murine models) was assessed." (PMID 40247106, 2025). "High levels of SLAMF7 were reported in hematologic malignancies such as chronic lymphocytic leukemia, diffuse large B-cell lymphoma, multiple myeloma, and myelodysplastic syndromes." (PMID 41168829, 2025). "Whilst SLAMF7 is upregulated in myeloma, it is expressed in other cell types such as NK cells, NK-like T cells and CD8+ T cells." (PMID 40247106, 2025). "Firstly, E1A expression increased over time in the majority of myeloma cells, which showed a strong positive correlation with SLAMF7 expression (p < 0.0009 and an R2 of 0.9264)." (PMID 40247106, 2025). "We investigated a novel SLAMF7-promoter driven oncolytic adenovirus (Ad[CE1A]) as a potential therapeutic for multiple myeloma, an incurable hematological malignancy." (PMID 40247106, 2025). "SLAMF7 is highly expressed on myeloma cells at all disease stages, with a limited expression on normal tissues, and, potentially, with few side effects." (PMID 41228264, 2025). "CS1, also known as CD319, SLAMF7, and CRACC, is a cell surface glycoprotein, which is highly expressed on multiple myeloma (MM) cells both at diagnosis and at relapse." (PMID 37848634, 2024). "These anti-SLAMF7 CAR T cells effectively killed myeloma cells in patient samples and a murine xenograft model." (PMID 38800372, 2024). "Collectively, these studies indicate the potential of anti-SLAMF7 CAR-T cells in myeloma treatment, though the implications of fratricide require more research." (PMID 39468695, 2024). "Instead, a unique activation pathway promotes SLAMF7–SLAMF7 interaction between NK and myeloma cells." (PMID 38410372, 2024). "The intensity of SLAMF7/CD319 expression in BC2 cells was comparable to that of OPM2 multiple myeloma cells." (PMID 38612827, 2024). "Elotuzumab (Empliciti) is a monoclonal antibody that targets signaling lymphocytic activation molecule F7 (SLAMF7), a protein that is highly expressed on the surface of myeloma cells and natural killer cells." (PMID 39065666, 2024). "SLAMF7 is a decent target for CAR T cell therapy because of its high expression on myeloma cells and low expression on normal cells." (PMID 37251372, 2023). "Of these three conserved genes upregulated in the lytic cells between both data sets, SLAMF7 encodes for a surface-expressed protein SLAMF7/CD319, which is a robust marker of plasma cells, especially in multiple myeloma and plasmablastic lymphoma (59, –, 61)." (PMID 37971257, 2023). "Our analysis showed BCMA, ICAM3 (CD50), CD221, and CS1 (SLAMF7) as the most abundantly expressed markers on PCs across all myeloma stages, with BCMA, ICAM3, and CD221 having significantly higher expression levels on disease versus precursor PCs." (PMID 37723227, 2023). "Elotuzumab, which, unlike anti-CD38 drugs, lacks single-agent activity, works through the direct activation of SLAMF7 on both myeloma cells and NK cells to kill myeloma cells via ADCC." (PMID 37958658, 2023). "SLAMF7 is a 66 kDa type 1 transmembrane protein that is expressed on myeloma cells and immune cells." (PMID 37754488, 2023).
myeloma (continued). "SLAMF7 is present on myeloma cells, and it promotes cell death through the interaction with the Fc receptors placed on specific cells of the immune system." (PMID 36834545, 2023). "SLAMF7 is an attractive therapeutic target in multiple myeloma, and a monoclonal antibody that targets SLAMF7 has shown consistent beneficial outcomes in clinical trials to date." (PMID 37754488, 2023). "SLAMF7 is up-regulated by about 97% of myeloma cells, although its expression in normal cells is limited." (PMID 37251372, 2023). "In several clinical trials, the SLAMF7 monoclonal antibody elotuzumab has shown a great advantage in combination with other therapies for the treatment of relapsed or refractory multiple myeloma (RRMM)." (PMID 36749634, 2023). "In cells lacking EAT-2 expression, following the homotypic interaction SLAMF7 between immune cells and myeloma cells, SHIP-1 recruitment is occurred, which requires tyrosine residue (Y-284) in the ITSM motif of SLAMF7." (PMID 37251372, 2023). "This study retrospectively investigated bone remineralization in patients with newly diagnosed multiple myeloma under a quadruple induction therapy of carfilzomib, lenalidomide, dexamethasone and the anti-SLAMF7 monoclonal antibody elotuzumab." (PMID 37568823, 2023). "Elotuzumab is an anti-signaling lymphocytic activation molecule F7 (SLAMF7) monoclonal antibody, which is used to treat relapsed/refractory multiple myeloma (MM)." (PMID 38143697, 2023). "Elotuzumab directly activates NK cells through SLAMF7 and Fc receptors, enhancing their anti-myeloma activity in vitro." (PMID 36834545, 2023). "Studies have focused on the functions of SLAMF7 as an important immune checkpoint in multiple myeloma (MM) immunotherapy." (PMID 36749634, 2023). "This project focuses on an anti-SLAMF7 CAR-T cell in multiple myeloma, which is manufactured virus-free." (PMID 36831349, 2023). "Our analysis confirms both CD221 and CS1 (SLAMF7) to be highly expressed in myeloma cells, in agreement with previous studies." (PMID 37723227, 2023). "The CARAMBA clinical trial (Phase 1/2; EudraCT No. 2019-001264-30/CARAMBA-1) is evaluating the safety, feasibility, and anti-myeloma efficacy of autologous SLAMF7 CAR T cells." (PMID 38006053, 2023). "SLAMF7 is a cell surface receptor involved in natural killer cell activation that received approval for treating multiple myeloma." (PMID 36727078, 2022). "It has been reported that SLAMF7-CAR T cells attack myeloma and confer selective fratricide of SLAMF7-positive normal lymphocytes." (PMID 36618390, 2022). "Compared with BCMA, SLAMF7 is a surface glycoprotein and is more evenly expressed on myeloma cells and less on B cells." (PMID 36261831, 2022). "Elotuzumab induces NK cell cytotoxicity against myeloma cells directly thought ADCC or indirectly by facilitating SLAMF7-SLAMF7 interactions between NK cells and myeloma cells to enhance natural cytotoxicity." (PMID 35493522, 2022). "The function of SLAMF7 is poorly understood, but previous evidence indicates its similar role as growth factor contributing to myeloma cell proliferation." (PMID 36618390, 2022). "Other newer treatment schemes for induction for multiple myeloma with bortezomib include the anti-SLAMF7 monoclonal antibodies, such as elotuzumab." (PMID 36354730, 2022). "Elotuzumab is approved for the treatment of multiple myeloma and functions primarily via antibody-dependent cellular cytotoxicity, but has also been shown to have SLAMF7 agonistic activity." (PMID 36199066, 2022). "SLAMF7 on NK cells can bind to elotuzumab, thereby inducing NK cell activation and enhancing cytolytic function against myeloma cells." (PMID 36263048, 2022). "When we compared immunohistochemical stainings of SLAMF7 on bone marrow myeloma cells before treatment and on extramedullary myeloma cells after treatment, we found strong and consistent SLAMF7 expression in all cases." (PMID 33575947, 2021).
myeloma (continued). "PVX-410 utilizes four peptide antigens targeting X-Box Binding protein 1, CD138, and SLAMF7, each of which were demonstrated to induce a myeloma-specific T cell response." (PMID 34638271, 2021). "SLAMF7 is a transmembrane receptor expressed on myeloma cells that plays a role in myeloma cell homing to the bone marrow." (PMID 33575947, 2021). "In conclusion, our analyses demonstrate limited efficacy of current elotuzumab-based IMiD combination treatments in patients with EMD, despite strong and consistent presence of SLAMF7 on extramedullary myeloma cells." (PMID 33575947, 2021). "Here we show that hemibodies addressing CD38 and SLAMF7 recruit T cells for the exquisite elimination of dual antigen positive multiple myeloma cells while leaving single antigen positive bystanders unharmed." (PMID 33420283, 2021). "As an exemplary and novel target for SB-based CAR-T cells, the CARAMBA consortium has selected the SLAMF7 antigen in multiple myeloma." (PMID 33846552, 2021). "Targeted therapy against SLAMF7 acts by activating antibody-dependent cell-mediated cytotoxicity against multiple myeloma cells by binding to the Fc region of antibodies by CD16." (PMID 34322356, 2021). "We have previously shown that coordinate SLAMF7 expression on both NK cells and myeloma target cells significantly enhances natural cytotoxicity responses, since SLAMF7 is a co-stimulatory receptor in NK cells." (PMID 33435153, 2021). "After informed consent was obtained, we next assayed expression levels of the BCMA, CD38, and SLAMF7 antigens on 30 primary myeloma cells from clinical bone marrow samples collected at our institution." (PMID 33420283, 2021). "SLAMF7-chimeric antigen receptor (CAR) T cells eliminate not only myeloma cells but also SLAMF7high NK and T cells." (PMID 33597728, 2021). "Considering that a functional relevance of SLAMF7 for the homing of myeloma cells to the bone marrow was postulated, our findings suggest that SLAMF7 does not imperatively restrict myeloma cells to the bone marrow microenvironment." (PMID 33575947, 2021). "In search of reasons for the relatively poor response and outcome rates in the investigated patient collective, we considered reduced expression of SLAMF7 on the myeloma cells at extramedullary sites as a potential mechanism for limited elotuzumab efficacy." (PMID 33575947, 2021). "For instance, the anti-SLAMF7 therapy against multiple myeloma (MM) included a dimerization domain fused to a caspase-9 domain suicide gene to mitigate the risk of off-target activation, as SLAMF7 is expressed on healthy leukocytes, including NK cells." (PMID 34452392, 2021). "Here, we demonstrate that the cell membrane protein SLAMF7 was highly expressed on immunosuppressive CD8+CD28-CD57+ Tregs in multiple myeloma (MM)." (PMID 33597728, 2021). "SLAMF7 (CD319) is a robust marker of malignant plasma cells in multiple myeloma and was shown to be responsible for the phagocytosis of cells after disruption of the tumor surveillance checkpoint CD47-SIRPα." (PMID 33995387, 2021). "The importance of SLAMF7 was described in multiple myeloma, where elotuzumab was approved to treat disease relapse." (PMID 33828555, 2021). "CD38 and CD319, which is identified with SLAMF-7, are expressed independently of maturation of myeloma cells." (PMID 33435539, 2021). "CS1, which is also referred to as CD319 or SLAMF7, is specifically expressed at high level in normal plasma cells and myeloma cells, and play an important role in myeloma parthenogenesis." (PMID 33504363, 2021). "In multiple clinical trial studies, anti-SLAMF7 CAR-T cells were investigated against myeloma cells." (PMID 33781320, 2021). "Primary myeloma cells and human myeloma cell lines express higher levels of SLAMF7 than the normal or reactive counterpart, as consequence of genetic derangements." (PMID 34307150, 2021).